MYC (MYC proto-oncogene, bHLH transcription factor)
Diseases named in the same sentence as MYC in open-access papers (continued):
Sharing a sentence is not in itself a finding about the gene and the disease.
cancer (continued). "Moreover, the extent to which EVs are elevated in cancer depends on the amplified genes in that cancer; for example, MYC and AURKB promote the release of some of the highest EV numbers." (PMID 36139610, 2022). "The notably high overlapping ratios were discerned for TFs playing critical roles in transcription pre-initiation or RNA polymerase activities, e.g., UBTF, TAF1, and POLR2A, in addition to others, like E2F6, IRF1, and MYC, which are involved in cancer-related processes." (PMID 36092921, 2022). "Moreover, ALDHs are markers of cancer stem-like cells and regulate signaling transduction, such as canonical RA signaling, c-MYC, cyclinD1 and PDK1/AKT." (PMID 36300093, 2022). "MYC tightly regulates the normal state, but dysregulation of MYC is prevalent in cancer." (PMID 35039581, 2022). "Our results suggest that inhibition of HDAC6 can be used to target excessive MYC in cancer." (PMID 36068335, 2022). "In this MYC dependency plot, significant MYC dependency was noted in multiple myeloma (MM) cancer cells, in line with frequent 8q24 translocation that leads to MYC overexpression in MM cancers." (PMID 35879727, 2022). "Ectopic MYC expression in cancer drives aerobic glycolysis and oxidative phosphorylation." (PMID 35281118, 2022). "By suppressing MYC activity, cancer cells can also become resistant to chemotherapy." (PMID 36139513, 2022). "Furthermore, we demonstrate a cancer cell-intrinsic role for MYC in suppressing inflammatory pathways." (PMID 36323660, 2022). "Likewise, cancer cells surviving the treatment with standard chemotherapeutic compounds displayed higher MYC expression levels." (PMID 35158939, 2022). "The MYC gene locus is subjected to copy number gains in numerous cancers, including CRC." (PMID 36139061, 2022). "Recently, we found that a major oncogene in cancer, MYC, becomes deregulated in MRT through loss of SNF5, a finding that explains the activation of MYC target gene signatures observed in SMARCB1-deficient cancers." (PMID 35650187, 2022). "However, their potential efficacy as treatment options in MYC-driven cancers remains to be explored." (PMID 34937878, 2022). "In three cohorts, 15 pathways were activated in patients with high HPRS, among which epithelial-mesenchymal transition, E2F targets, G2M checkpoint, MYC targets, angiogenesis, and DNA repair were all important pathways affecting the occurrence and development of cancer." (PMID 35942407, 2022). "Using bioinformatic tools to find common putatively actionable alterations in a set of 33 types of cancer (including GBMs), it was found that across the entire data set, CDKN2A deletions (13%), PIK3CA mutations (12%), MYC amplifications (8%), and K-RAS mutations (7%) were the most common." (PMID 35626024, 2022). "•Proteomics for isogenic and cancer-derived models of c-MYC, AKT, BRAF, EGFR, HER2, KRAS, and MEK." (PMID 35594991, 2022). "Overexpression of c-MYC leads to the up-regulation of anti-apoptotic proteins in cancer cells." (PMID 35267559, 2022). "c-MYC is documented to be one of the most up-regulated oncogenes in different types of cancers." (PMID 35267559, 2022). "Overexpression of PLCG1 was correlated with five essential cancer-related processes and pathways: protein secretion, MYC targets, mitotic spindle, G2/M checkpoint, and E2F targets, which demonstrates that PLCG1 is possibly involved in the facilitation of cancer proliferation and adaptation." (PMID 34697421, 2022). "Besides, NRF1 up-regulated E2F1 expression transcriptionally, then orchestrated both c-MYC and E2F to regulate their target genes for cancer proliferation." (PMID 35448958, 2022). "Many cancers exhibit abnormal MYC expressions, including MM." (PMID 36672841, 2022).
cancer (continued). "A study demonstrated that the down-regulation of ribosome protein RPL24 could reduce the rate of ribosome biogenesis and improve disease-free survival in the mouse cancer model with MYC overexpression." (PMID 35267559, 2022). "In this context, a new series of 12 dibenzoquinoxaline derivatives was obtained, and, among them, compounds 13–15 were potent TopoI and c-MYC transcription inhibitors, also inhibiting cancer cell growth in TNBC cell lines, with IC50 values in the range of 1.0 μM." (PMID 36428499, 2022). "We next examined the effect of MYC expression changes on cancer cell survival." (PMID 35844787, 2022). "Thus the promotion of ribose 5-phosphate production through both forward oxidative and reversed non-oxidative pathways and the promotion of nucleotide biosynthesis and catabolism are driven by MYC in cancer cells." (PMID 35945217, 2022). "As the oncogenic function of LINC00958 has been reported in multiple cancer types, MYC/MAX, a vital oncogenic transcription factor in various cancers, may contribute to the transcriptional regulation of LINC00958 in cancer." (PMID 35223488, 2022). "Transcription factor MYC plays a central role in cancer by inducing autophagy." (PMID 35874628, 2022). "Moreover, MYC upregulation was shown to impose a transcriptional stress to cancer cells that increases their dependency on the proper functionality of the splicing machinery." (PMID 35530315, 2022). "However, in this case, the c-MYC transcription and expression were downregulated in cancer cells treated with the iM stabilizer B19." (PMID 35337098, 2022). "In addition, gene ontology analyses of the clinical GC cohort revealed significant correlation between IFITM3-associated genes and targets of c-MYC, which is a crucial downstream effector of HGF/MET pathway in cancer progression." (PMID 35941699, 2022). "Importantly, the 20S proteasome enhancer was well tolerated both in mice and in canines, validating this new approach for further therapeutic assessment for various MYC-driven cancers." (PMID 35625675, 2022). "Both c-MYC and HIF1α act together to promote cancer cell growth and progression." (PMID 36818371, 2022). "The transcription factor c-MYC drives growth and proliferation in most cancers." (PMID 35159073, 2022). "Given that c-MYC was an oncogene and played important roles in promoting cell proliferation of cancer cells, the downregulation of c-MYC by dBET1 at least partially explained the observed arrested cell cycle, indicating c-MYC as a downstream effector of dBET1’s cytotoxic effects." (PMID 35832114, 2022). "The oncogene MYC is a TF that drives cancer development and progression." (PMID 36316442, 2022). "Since the phenotype of so-called cancer stem-like cells (CSCs) is a known feature of many chemotherapy-resistant tumors, it was then investigated whether MYC and MCL1 contributed to the enrichment of CSCs." (PMID 36501221, 2022). "Additionally, T-025, an inhibitor of CDC2-like kinases, which control mRNA splicing, induces alternative splicing and death of MYC-hyperactivated cancer cells." (PMID 35439169, 2022). "Chromatin immunoprecipitation and additional research revealed that this H3K27 acetylated NAMPT enhancer binds to the transcription factors MAX and c-MYC, which control its activity, and performs substantially better exclusively in cancer cells that are dependent on the salvage pathway." (PMID 36160449, 2022). "This could indicate that CDK7 and CDK9 contribute to cancer cell fitness through regulation of different aspects of the MYC transcriptional network." (PMID 36577800, 2022). "However, the low expression group had significantly highly expressed E2F targets and MYC targets, both of which participated in progression of most cancers." (PMID 35933370, 2022). "Moreover, there are many other cancers that actively select for MTBP overexpression as well as cancers that rely on high MYC activity." (PMID 35741402, 2022).
cancer (continued). "Previous studies have suggested that c-MYC, as well as other oncogenes, can be overexpressed in cancer due to the activity of histone modifying proteins such as histone acetyltransferases (HAT), or histone readers such as bromodomain and extra-terminal domain (BET) proteins." (PMID 36313707, 2022). "c-MYC is aberrantly expressed in up to 50% of human cancers." (PMID 36233342, 2022). "Ectopic c-MYC expression could drive aerobic glycolysis in cancers via the direct upregulation of GLUT1, LDHA, HK2, and PKM2." (PMID 35571245, 2022). "Furthermore, the cancer cells adapt to avoid the UPR cell death signals as illustrated by the MYC Proto-Oncogene example." (PMID 36230792, 2022). "Thus, we propose that MYC-EMSLR-LncPRESS1 pathway is functional in cancer cells based on the following results: First, LncPRESS1 was upregulated after depletion of EMSLR." (PMID 35169159, 2022). "Recent studies have demonstrated that drugs that inhibit ribosome biogenesis or that target c-MYC might offer a viable therapeutic approach for cancer treatment." (PMID 35267559, 2022). "In addition, study has pointed out that TF MYC was usually expressed constitutively in cancer, which led to an increased expression of many genes, some of which were involved in cell proliferation, in turn leading to cancer formation." (PMID 35743172, 2022). "MYC is a major oncogene that plays an important role in cell proliferation in human cancers." (PMID 35887071, 2022). "Moreover, one study reported that knocking down IGF2BPs greatly reduced MYC expression and hindered cancer cell proliferation, colony forming ability, and cell migration/invasion, mimicking the effect of MYC silencing." (PMID 36091006, 2022). "MYC cancer cell survival and proliferation programs play a major role." (PMID 35626024, 2022). "Furthermore, we found a key gene, such as MYC, by constructing a network of cancer related pathways with differentially expressed genes and transcription factor analysis." (PMID 36331666, 2022). "Interestingly, c-MYC, an important transcription factor for pluripotent stem-cell metabolism, as well as for metabolic reprogramming in cancer cells, mediates the expression of glycolytic genes, such as ldha." (PMID 36430764, 2022). "Here, we review the known links between MYC and either resistance or sensitization to therapeutic intervention, and draw future perspective to exploit these pharmaco‐genetic interactions toward improved cancer patient outcomes." (PMID 36214609, 2022). "MYC, a basic-helix-loop-helix (bHLH) family TFs were initially discovered from a homology study between an oncogene carried by the Avian virus, Myelocytomatosis (v-MYC) and a human gene overexpressed in different cancers, cellular MYC (c-MYC)." (PMID 36119617, 2022). "Two of the individual CTCs (CTC1 and CTC2) and the CTC pool had homogenous copy-number profiles, and included amplification on 1q and 8q (MYC), 11q (CCND1, FGF3, FGF4) and allelic loss of regions including several cancer genes on 3p (BAP1), 13q(RB1, BRCA2) and 17p (MAP2K4)." (PMID 36088510, 2022). "For example, MYC proteolytic stability and MYC transcriptional activity are highly regulated by multiple E3 ligases, many of which are intrinsically disordered, overexpressed in cancer, and positively regulate MYC transcription." (PMID 35625675, 2022). "The expression of MYC is tightly controlled in normal cells by a range of upstream and downstream mechanisms at the genetic, mRNA and protein levels, but it becomes dysregulated and overexpressed in over 70% of human cancers." (PMID 35328482, 2022). "MYC is a well‐known regulator of metabolic reprogramming in cancer, including lipid metabolism." (PMID 36536477, 2022).
cancer (continued). "Though POLR3G expression broadly correlates with MYC levels across all cancer types, whether and to what degree MYC activity overlaps OCT4, NANOG, and potentially other context-specific master transcription factors remain important questions." (PMID 36710885, 2022). "In addition, transcriptional regulation of cancer pathways, such as transcriptional misregulation in cancer (ecb05202, e.g., MYC, MLLT10) and microRNAs in cancer (ecb05206, e.g., MIR125B), were enriched." (PMID 36553455, 2022). "Majority of human cancers exhibit increased expression of MYC and its family members, leading to global metabolic reprogramming, which in turn provides energy sources and redox potential to support uncontrolled proliferation of cancer cells." (PMID 35908258, 2022). "The prognostic significance of the nuclear expressions of FAM83H and SCRIB might be related to their roles in cancer progression in conjunction with nuclear proteins important in cancer progression, such as MYC and β-catenin." (PMID 35885485, 2022). "Abnormal MYC expression is the most common abnormality in malignant tumours." (PMID 36482116, 2022). "c-MYC can regulate various cellular metabolisms, including glucose and glutamine, which are essential for generating enough energy and intermediates of macromolecules to support the high rate of cancer cell proliferation." (PMID 35267559, 2022). "MYC is an essential molecular hub in CML pathophysiology and could actively participate in the dysregulation of PTBP1 and hnRNPA1 as well as PRMT5 and SRSF1, genes deregulated by MYC in other cancers." (PMID 36230624, 2022). "Whether such a multilayer buffering system contributes to the heterogeneity of the PRMT5i sensitivity of cancers with high MYC expression remains to be deciphered in future work." (PMID 35439169, 2022). "Notably, the expression levels of both BRD4 and MYC were elevated in HCT116 cancer cells compared with those in the normal colorectal cell line ccd18co." (PMID 35159127, 2022). "MYC amplification, for instance, in humans is most commonly found in tumors of the basal-like subtype, and has previously been reported in canine mammary gland tumors with a simple carcinoma histology." (PMID 35932380, 2022). "For these reasons, MYC has long been considered an ideal cancer target." (PMID 34359754, 2021). "MYC has been reported to be a transcriptional activator for lncRNAs in human cancers." (PMID 33407499, 2021). "We performed RT-qPCR and confirmed the differential expression of several cancer driver genes: increased mRNA expression of oncogenes MYC and PIK3CG, as well as decreased expression of tumor suppressor genes CDKN1A and EPHA2, was observed in the H2BE76K mutant cells." (PMID 33548228, 2021). "The oncoprotein MYC is found deregulated in many human cancers." (PMID 33801599, 2021). "High levels of this circRNA enhance MYC gene transcription and cancer cell proliferation." (PMID 34440124, 2021). "CSNK2A1 engages the MYC, Akt, and NFκB pathways to stimulate the proliferation of cancer cells." (PMID 34359939, 2021). "The results included well-known cancer genes such as MYC, FOXA2 and FADD, and the unknown SLITRK3 gene." (PMID 35006496, 2021). "YY1 is a known indirect inhibitor of MYC involved in cancer development." (PMID 33502086, 2021). "In other cancer models miR-145 has also been shown to regulate MYC." (PMID 33760831, 2021). "Interestingly, positively correlated loci represented cancer driver genes (MYC, PRKCD, RB1, CDK6), molecules involved in immune response (MALT1, PIK3CG), as well as cellular and hormonal signaling (HGF, PTPN13, IGF1, SMAD1, ESR1, CTGF)." (PMID 34368147, 2021). "HAT inhibitors (HATi) therefore represent attractive weapons against MYC-driven cancers." (PMID 33801599, 2021).
cancer (continued). "It is tempting to speculate that HTOL-based therapeutics, through the inhibition of these potent oncogenic drivers, might provide new options applicable not only to MM but also to other c-MYC-addicted cancer types." (PMID 34769070, 2021). "It has been reported that lncRNA SNHG1 could directly interact with FUBP1 central domain and resist the binding between FIR and FUBP1, thereby modulating the oncogene MYC transcription and promoting cancer development." (PMID 34116677, 2021). "Perhaps somewhat contradictorily, two studies of HPV+ head and neck squamous cell carcinoma tissue samples did not identify an association between the cancer and increased MYC expression." (PMID 34066504, 2021). "Transcription factor genes (OCT4, KLF4, SOX2, MYC, NANOG, and REX1) and cell surface markers (CD133, LGR5), which are associated with embryonic stem cells, induced pluripotent stem cells, and cancer stem cells, have been selected for measuring expression levels from the selected tissues." (PMID 34452555, 2021). "Increased activity or expression of MYC has been reported in more than half of human cancers." (PMID 34203763, 2021). "In cancer, MYC levels are greatly enhanced, and in some cases, by orders of magnitude." (PMID 33799592, 2021). "MYC is a proto-oncogene frequently observed in numerous human cancers." (PMID 34202548, 2021). "Additionally, the transcription factor and proto-oncogene MYC plays an essential role in cancer and tumor progression." (PMID 34445612, 2021). "MYC heterodimers (e.g., MYC/MAX) bind to cis-regulatory E-box sequences of numerous genes involved in the regulation of growth, proliferation, or metabolism, thereby serving all hallmark demands of cancer cells." (PMID 34637026, 2021). "MYC amplification is found across many types of cancers with an estimated overall frequency of 14%." (PMID 34535639, 2021). "UBE2I is an anti-cancer target for cancers driven by MYC and RAS/RAF." (PMID 33810518, 2021). "In addition, NG25 down-regulates MYC which can render cancer cells less resilient to genotoxic stress." (PMID 34676048, 2021). "Therefore, MYC marks cancers with a specific set of therapeutic vulnerabilities, which should consequently facilitate the stratification of patients for precise therapeutic interventions." (PMID 33071285, 2021). "The oncogene MYC promoter G4 (MycG4) is the most prevalent G4 in human cancers." (PMID 33978746, 2021). "In contrast, in cancer cells, miR-494 has been reported to target MYC and PGC-1α." (PMID 35008652, 2021). "The high expression of AURKA has been seen in many sorts of cancers such as ovarian, liver, and colorectal ones making some oncogenic factors like c‐MYC, NF‐kB, and β‐catenin active, and it could lead to chromosomal instability." (PMID 34337875, 2021). "Therefore, it was promising to target MYC and its interacting partners as therapeutic targets in cancer therapy." (PMID 36303724, 2021). "MYC is a proto-oncogene and has been well documented in cancer initiation and progression." (PMID 34671559, 2021). "One of the oncogenes that has been widely studied in a plethora of cancers is c-MYC." (PMID 34641286, 2021). "MYC is one of the most frequently amplified protein-coding genes in cancer." (PMID 34885058, 2021). "Consequently, the ATR/CHK1 pathway represents a vulnerability for tumors in which latent RS can be awakened and, consistently, MYC-driven cancers are highly sensitive to ATR and CHK1 inhibitors as single agents." (PMID 34201047, 2021). "In addition, DDX39 was found to be positively correlated with proto-oncogene MYC activation and cancer cell cycle acceleration in bioinformatic analysis, and with immune cell infiltration and the antigen presentation process as well." (PMID 34421357, 2021). "MYC renders cancer cells dependent on a properly functioning transcriptional machinery." (PMID 34637026, 2021).